POLD3 (DNA polymerase delta 3, accessory subunit)
Description:
Accessory component of both the DNA polymerase delta complex and the DNA polymerase zeta complex. As a component of the trimeric and tetrameric DNA polymerase delta complexes (Pol-delta3 and Pol-delta4, respectively), plays a role in high fidelity genome replication, including in lagging strand synthesis, and repair. Required for optimal Pol-delta activity. Stabilizes the Pol-delta complex and plays a major role in Pol-delta stimulation by PCNA. Pol-delta3 and Pol-delta4 are characterized by the absence or the presence of POLD4. They exhibit differences in catalytic activity. Most notably, Pol-delta3 shows higher proofreading activity than Pol-delta4. Although both Pol-delta3 and Pol-delta4 process Okazaki fragments in vitro, Pol-delta3 may also be better suited to fulfill this task, exhibiting near-absence of strand displacement activity compared to Pol-delta4 and stalling on encounter with the 5'-blocking oligonucleotides. Pol-delta3 idling process may avoid the formation of a gap, while maintaining a nick that can be readily ligated. Along with DNA polymerase kappa, DNA polymerase delta carries out approximately half of nucleotide excision repair (NER) synthesis following UV irradiation. In this context, POLD3, along with PCNA and RFC1-replication factor C complex, is required to recruit POLD1, the catalytic subunit of the polymerase delta complex, to DNA damage sites. Under conditions of DNA replication stress, required for the repair of broken replication forks through break-induced replication (BIR). Involved in the translesion synthesis (TLS) of templates carrying O6-methylguanine or abasic sites performed by Pol-delta4, independently of DNA polymerase zeta (REV3L) or eta (POLH). Facilitates abasic site bypass by DNA polymerase delta by promoting extension from the nucleotide inserted opposite the lesion. Also involved in TLS, as a component of the tetrameric DNA polymerase zeta complex. Along with POLD2, dramatically increases the efficiency and processivity of DNA synthesis of the DNA polymerase zeta complex compared to the minimal zeta complex, consisting of only REV3L and REV7.
Synonyms: KIAA0039; P66; P68; PPP1R128; IMD122
Tractability: Small molecule: an approved drug acts on it; a structure with a bound ligand is known. PROTAC: UniProt records ubiquitination sites on it; ubiquitination databases record sites on it; its protein half-life has been measured.
Target class: Enzyme
Gene: Protein-coding gene on chromosome 11 (74,493,851 to 74,669,117, forward strand). Ensembl gene ENSG00000077514.
Subcellular location: Cytoplasm; Nucleus
Subcellular location (Human Protein Atlas): Nucleoplasm
Pathways (Reactome):
DNA Repair: Dual Incision in GG-NER; Dual incision in TC-NER; Gap-filling DNA repair synthesis and ligation in GG-NER; Gap-filling DNA repair synthesis and ligation in TC-NER; HDR through Homologous Recombination (HRR); PCNA-Dependent Long Patch Base Excision Repair; Recognition of DNA damage by PCNA-containing replication complex; Termination of translesion DNA synthesis
Cell Cycle: Polymerase switching on the C-strand of the telomere; Processive synthesis on the C-strand of the telomere; Removal of the Flap Intermediate from the C-strand; Telomere C-strand (Lagging Strand) Synthesis
DNA Replication: Polymerase switching; Processive synthesis on the lagging strand; Removal of the Flap Intermediate
Gene Ontology:
Molecular function: protein binding; protein-macromolecule adaptor activity; DNA-directed DNA polymerase activity
Biological process: DNA biosynthetic process; DNA-templated DNA replication; error-prone translesion synthesis; nucleotide-excision repair, DNA gap filling; DNA strand elongation involved in DNA replication; DNA synthesis involved in DNA repair; DNA synthesis involved in UV-damage excision repair; mismatch repair; DNA replication
Cellular component: delta DNA polymerase complex; nucleoplasm; nucleus; zeta DNA polymerase complex; cytoplasm
Genetic constraint (gnomAD): Loss-of-function variants: 4 observed, 22.35 expected, observed/expected ratio (o/e) 0.18, 90% interval 0.087 to 0.41. The upper end of that interval is the gene's LOEUF score, 0.41, which puts it in group 1 of 6, group 1 being the genes least tolerant of losing a copy. Missense variants: 280 observed, 299.02 expected, observed/expected ratio (o/e) 0.94, 90% interval 0.85 to 1.03. Synonymous variants: 95 observed, 109.43 expected, observed/expected ratio (o/e) 0.87, 90% interval 0.73 to 1.03.
Gene-disease validity (ClinGen):
ClinGen rates the evidence that POLD3 causes each of these diseases.
immunodeficiency 122 (autosomal recessive): Limited.
Homologues: Orthologues: chimpanzee POLD3 (96% identical), rabbit POLD3 (90% identical), dog POLD3 (87% identical).
Diseases named in the same sentence as POLD3 in open-access papers:
POLD3 is named in the same sentence as 25 diseases in open-access papers, as found by Europe PMC text mining. Sharing a sentence is not in itself a finding about the gene and the disease. The quoted sentences say what the papers report.
colorectal cancer (2 papers, 2015 to 2023). A primary or metastatic malignant neoplasm that affects the colon or rectum. "The aim of this study was to investigate the relationship between CHCHD3P1-HSP90AB7P, GRID1, HSPA12A, PRLHR, SBF2, POLD3, and C11orf93-C11orf92 genes and susceptibility to gastric and colorectal cancers in the Chinese Han population." (PMID 26302849, 2015). "The aim of this research was to study whether polymorphisms of CHCHD3P1-HSP90AB7P, GRID1, HSPA12A, PRLHR, SBF2, POLD3 and C11orf93-C11orf92 genes are associated with the risk of gastric and colorectal cancers in the Chinese Han population." (PMID 26302849, 2015).
hepatocellular carcinoma (1 paper, 2023). A malignant tumor that arises from hepatocytes. "The biomarkers MIR4435-2HG and lnc-POLD3-2, as well as their combinations, have been demonstrated to be effective in distinguishing between hepatocellular carcinoma and non-hepatocellular carcinoma." (PMID 37546394, 2023).
Lynch syndrome (1 paper, 2013). An autosomal dominant hereditary neoplastic syndrome characterized by the development of colorectal carcinoma and a high risk of developing endometrial carcinoma, gastric carcinoma, ovarian carcinoma, renal pelvis carcinoma, and small intestinal carcinoma. "Lynch syndrome tumors showed up-regulation of 1129 genes, e.g. genes involved in G1/S transition (CCNE, CCNH, E2F2 and CDK2), DNA replication (CDC45, RPA1, RFC5, MCM4 and POLD3) and chromosomal organization and mitosis (CCNB2, MLF1IP, CASC5, KIF2C and PLK4), which is in line with previous findings." (PMID 23951239, 2013).
neutropenia (1 paper, 2017). A decrease in the number of neutrophils found in the blood. "Polymorphisms in ERCC2, ERCC6, DDB2, RPA1, POLD1 and POLD3 presented significant association with neutropenia." (PMID 28924235, 2017). "In this study, POLD1 and POLD3 showed significant association with neutropenia." (PMID 28924235, 2017). "rs10857 and rs6592576 in POLD3 showed significant association with neutropenia in all patients." (PMID 28924235, 2017). "POLD3 presented consecutive significant signals on neutropenia." (PMID 28924235, 2017).
osteoarthritis (1 paper, 2023). A noninflammatory degenerative joint disease occurring chiefly in older persons, characterized by degeneration of the articular cartilage, hypertrophy of bone at the margins and changes in the synovial membrane. "The overall direction of genetic colocalization and phenotypic correlations are consistent, with exception of IL11 and POLD3/CHRL2 variants, where colocalization is anti-correlated with osteoarthritis, while phenotypically we see a positive correlation between DISH and OA." (PMID 37156767, 2023).
ovarian carcinoma (1 paper, 2016). A malignant neoplasm originating from the surface ovarian epithelium. "The network based approach identified two 7-gene functional interaction modules (31: DCLRE1A, EXO1, KIAA0101, KIN, PCNA, POLD3, POLD2; 35: DKK3, FABP3, IRF1, AIM2, GBP1, GBP2, IRF2) that are associated with prognosis of ovarian cancer patients." (PMID 27806724, 2016).
pancreatic cancer (1 paper, 2021). "A novel 14-gene signature comprising CCDC148, SH3RF2, CACNA1D, POLD3, PARP1, AP1M2, C4orf19, ANO1, VGLL1, SCEL, INPP4B, NET1, INSIG2 and BVES and a corresponding risk score formula were established for pancreatic cancer risk stratification and prognosis prediction." (PMID 33731794, 2021).
cancer (18 papers, 2017 to 2025). A tumor composed of atypical neoplastic, often pleomorphic cells that invade other tissues. "Recent studies have shown that the loss or reduced expression of POLD3 predicts the occurrence and progression of colorectal cancer and other malignant tumors." (PMID 34868924, 2021). "Polymorphisms and mutations in POLD1 and POLD3 were reported to be associated with cancer risk." (PMID 28924235, 2017). "This in turn instigates POLD3-mediated replication restart during the S-phase, collectively mimicking phenotypes observed in BRCA-deficient cancers." (PMID 41354653, 2025). "The authors propose that BIR mediated by POLD3 at compromised replication forks is responsible for genomic duplications in human cancers." (PMID 34226278, 2021). "Recent studies in ALT cancer cells found that telomere recombination can proceed through multiple mechanisms, including POLD3-dependent break-induced telomere synthesis and RAD52-dependent mitotic telomeric DNA synthesis." (PMID 32620872, 2020). "Mutations in the POLD1 and POLD3 genes increase the risk of CRC and other malignant tumors." (PMID 39458936, 2024). "POLD3 plays a specialized role in the repair of damaged replication forks, indicating that POLD3 activity may be particularly relevant for cancer cells enduring high levels of DNA replication stress." (PMID 34868924, 2021). "Research has shown that POLD3 plays a unique role in the process of RS-induced DNA break repair, so targeting POLD3 could provide a priority opportunity to target cancer cells." (PMID 32920549, 2020). "Considering that inhibition of Pol ζ, Pol δ or REV3 is toxic to normal cells, and perhaps unlikely to provide a suitable therapeutic index in vivo, inhibitors specifically targeting REV1 or its interaction with POLD3 might be a promising avenue to pursue for the development of a new cancer therapy." (PMID 36759509, 2023). "Moreover, we also uncover that loss of EXD2 is synthetic sick with BLM, DNA2 and POLD3, which could represent an attractive therapeutic target against ALT-dependent cancers." (PMID 37105990, 2023). "Our observations are of particular interest with respect to human cancers, which commonly elevate POLD2 and POLD3 levels, perhaps to compensate elevated levels of replication stress." (PMID 34226278, 2021). "Finally, we show that co-depletion of EXD2 with BLM, DNA2 or POLD3 confers synthetic lethality in ALT cells, identifying EXD2 as a potential druggable target for ALT-reliant cancers." (PMID 37105990, 2023). "To further establish whether the interplay between SETX and POLD3/BLM impacts genome stability, we examined genomic signatures in cancer databases with relation to SETX, POLD3 and BLM expression." (PMID 35440629, 2022). "Members of the BTR complex, POLD3, or other BIR-specific factors could also represent promising targets for ALT-specific cancer therapeutics." (PMID 31138797, 2019). "As a first step in testing this hypothesis, we carried out a pilot study to analyze the expression of five proteins (Ki-67, Cyclin E, POLD3, γH2AX and FANCD2) on a collection of 32 tumor samples from a representative range of cancer types (colon, lung, breast or stomach)." (PMID 28445142, 2017).
tumor (8 papers, 2017 to 2025). "Our own analysis of human POLD3 data from the Cancer Genome Atlas (TCGA) and The Genotype-Tissue Expression (GTEx) project, showed alteration of POLD3 expression in 34 types of tumor." (PMID 39596481, 2024). "Not only do our results discover upregulated expression of POLD3 in GC cell lines, GC xenograft models and clinical tumor tissue, but also link PLOD3 expression with poor survival outcomes in GC patients." (PMID 35835735, 2022). "In addition, variants in MMR pathway genes, MSH3, MSH6, LIG1, MCM9, and POLD3, were associated with relatively high MSI score and/or high mutational burden in 6 tumor samples." (PMID 41353477, 2025). "The differential analysis filtered for processes driven by CD271 in tumor-initiating cells also revealed enrichment for the genes participating in nucleotide excision repair (NER, including damage recognition and repair factor XPC, DNA repair associated BRCA2, UBE2I, COPS7A, POLD3, USP45, RFC5)." (PMID 31118427, 2019). "Tumor related events such as DNA replication (EXO1, p = 0.036) and mismatch repair (POLD3, p = 0.011) were altered in primary and recurrent tumors." (PMID 39217365, 2024).
infection (2 papers, 2020). The state of being infected such as from the introduction of a foreign agent such as serum, vaccine, antigenic substance or organism. "Our data suggest that the accessory components (RFC2, RFC3, RFC5, PCNA), polymerases (POLD1, POLD2, POLD3, POLE, POLE2, POLE4), and ligase LIG1, were downregulated during infection, for which the downregulation of RFC5, POLD1, POLD2, POLD3, POLE, and LIG1 was CagA-related." (PMID 33339161, 2020).
neurological disorders (1 paper, 2022). "Most importantly, several DEGs such as CX3CL1, SEMA3F, OPHN1, POLA2, MCM10 and POLD3 were found to be associated with neuronal/brain process and genome stability, that is known to be relevant during neurological disorders." (PMID 36267332, 2022).
POLD3 also shares sentences with these, for which no sentence is quoted: Fanconi anemia (3 papers); gastric cancer (2); glioma (2); gout (2); allergic rhinitis (1); liver cancer (1); lung adenocarcinoma (1); Omenn syndrome (1); osteosarcoma (1); promyelocytic leukemia (1); psoriasis (1); serous ovarian carcinoma (1); small cell lung carcinoma (1); stomach cancer (1).